CD4 (CD4 molecule)
Diseases named in the same sentence as CD4 in open-access papers (continued):
Sharing a sentence is not in itself a finding about the gene and the disease.
heart failure (61 papers, 2012 to 2025). Inability of the heart to pump blood at an adequate rate to meet tissue metabolic requirements. "A previous study reports a strong association between peripheral circulating CD4+ T-cell subsets and the occurrence of heart failure and atherosclerotic CVD." (PMID 39812046, 2025). "Lastly, we recognized that CCR2+ cardiac macrophages are not the only immune cells to be implicated in ventricular remodeling; for instance, CD4+ T cells also play an important role in the transition from cardiac hypertrophy to heart failure." (PMID 37115698, 2023). "In iPAH patients, the percentages of CD4+CTLA-4+ T cells correlated strongly positively with the severity of heart failure New York Heart Association (NYHA) Functional Classification (r = 0.7077, p < 0.001)." (PMID 36555549, 2022). "The percentages of CD4+CTLA-4+ T cells correlated strongly positively with the severity of heart failure New York Heart Association (NYHA) Functional Classification (Spearman’s rank correlation r = 0.7077, p < 0.001)." (PMID 36555549, 2022). "Heart failure was detected in mice with pathogenic CD4+ T cell transfer under stress condition by a cardiac electrocardiogram system, suggesting a heart failure at least partially mediated by high potassium ions." (PMID 28809157, 2017). "Activated CD4 T-cell subsets are associated with the progression of heart failure, and the activation of peripheral blood CD3 T lymphocytes is associated with atrial fibrillation." (PMID 28726529, 2017). "Recently, the pathogenic role of CD4+ T cells in pressure overload-induced cardiac remodelling and in the transition to heart failure was demonstrated in animal models." (PMID 27135610, 2016). "Taken together, these findings suggest that ischemic heart disease drives a broad depletion of CD4+ cells, weakening the adaptive immune repertoire, while end-stage heart failure is associated with preserved CD4+ numbers but selective enrichment of CCR5+CXCR3+ inflammatory subsets." (PMID 41155153, 2025). "Clinically, it was also found that the high expression of CD4+ T cells in patients with heart failure is a strong predictor of all-cause and cardiovascular mortality in patients with heart failure and a potential marker for the progression of heart failure." (PMID 36186992, 2022). "In a recent study, HIV-infected individuals with detectable viral loads and low CD4 T cell counts were found to have an increased risk of heart failure, increased risk of cardiovascular death when compared to HIV-infected patients with high CD4+ T cell counts and undetectable viral loads." (PMID 32158701, 2020). "The effect of Dendritic cell Absolute Count, CD62l- CD86+ myeloid Dendritic cell Absolute Count, CD62l- CD86+ myeloid Dendritic cell% Dendritic cell, CD39+ CD8+ T cell% CD8+ T cell, CD3 on Central Memory CD4+ T cell on heart failure was positive." (PMID 38938655, 2024). "In myocardial samples from both young and elderly heart failure patients, three types of dysregulated immune cells were identified: Macrophages M1, T cells CD4 memory resting, and T cells regulatory." (PMID 38686376, 2024). "Compared to younger patients with heart failure, myocardial samples from elderly patients exhibit lower expression of CD4 memory resting T cells and higher expression of regulatory T cells." (PMID 38686376, 2024). "Through immune infiltration analysis, it was found that four hub genes can interact with Activated B cells, Activated CD4+ T cells, Immature B cells and Regulatory T cells to further affect dialysis patients with heart failure." (PMID 39844908, 2024). "In a murine model of heart failure, CD4+ T cells are activated after exposure to IsoLG-adducted cardiac peptides presented by class II MHC." (PMID 39145457, 2024). "Utilizing multiple mice strains including, RAG2-KO, CD8+-KO, and MHCII-KO, the authors found that CD4+T cells appear to be the primary drivers of cardiac fibrosis after TAC-induced heart failure." (PMID 36970367, 2023).
heart failure (continued). "In a study of mouse models with heart failure, CD4+ Foxp3+ Tregs were found to expand robustly in the heart and circulation for adverse cardiac remodeling, resulting in the suppression of circulating CD4+ T cells and systemic inflammation." (PMID 37273870, 2023). "They observed that CD4+ T cells become pathological during heart failure and that the expression of TNF-α and TNFR1 increases in these cells." (PMID 37626701, 2023). "After Shenfu Injection was used to treat 56 patients with heart failure and Kidney-Yang deficiency, the increased levels of CD4+CD25+Foxp3+Treg and CD4+ T cells were suppressed, while the low level of IL-10 was elevated." (PMID 36172573, 2022). "Consistent with previous findings, M2 macrophages are reduced in heart failure myocardial tissue, which in turn increases cardiac apoptosis and myocardial CD4+ T-cell accumulation." (PMID 36704339, 2022). "Treg, CD4+, CD8+ T cells, and the ratio of CD4+ to CD8+ T cells are expected to be biomarkers of heart failure." (PMID 36172573, 2022). "As it is already well known, the production of IFN-γ by the Th1 CD4+ T-lymphocytes are major contributors to heart failure." (PMID 34456907, 2021). "In heart failure models, the levels of circulating CD4+ T cells and CD4+ T cells infiltration in the LV were significantly increased, and the expression of IL-17 was upregulated." (PMID 34020615, 2021). "Previous reports have suggested that CD4+T cells are directly involved in the progression from hypertrophy to heart failure, yet the precise mechanism by which T cells promote heart failure remain to be clarified." (PMID 34745139, 2021). "The number of CD4+ Th cells subset Th17 cells infiltrated in the LV was increased significantly in the heart failure rabbit model." (PMID 34020615, 2021). "T cells are known to promote nonischemic heart failure, and the specific antigen recognition of CD4 T cells appears to be crucial for the progression from compensated cardiac hypertrophy to heart failure." (PMID 34776787, 2021). "In animal models of pressure overload-induced heart failure, recruited M1 macrophages communicate with CD4+ T lymphocytes and perpetuate the pro-inflammatory wave leading to fibrosis, cardiac dysfunction, and heart failure." (PMID 32528309, 2020). "The mechanisms by which activated CD4+ T cells contribute to heart failure progression remain unelucidated." (PMID 32327611, 2020). "We have recently demonstrated that possessing high numbers CD4+-T cells with specificity for an antigen in cardiomyocytes can accelerate progression into heart failure after TAC." (PMID 30498501, 2018). "In heart failure, the presence of circulating CD4+ T-cells (expressing inflammatory cytokines) tightly correlates with altered LV function, and probably contributes to the transition from cardiac adaptation to heart failure." (PMID 30177883, 2018). "All 10 patients were in heart failure and with advanced immunosuppression, with an average CD4 cell count of 83 cells/μl." (PMID 22331234, 2012). "When ACS occurred, the account of CD4+ T cells might reduce due to cardiomyocytes necrosis, fibrosis, and systolic dysfunction and lead to heart failure." (PMID 37118659, 2023). "CD4 T cells are closely involved in the progression of cardiac insufficiency." (PMID 35327947, 2022). "Additionally, CD4+ T cells persist, expand several weeks after cardiac injury, and contribute to heart failure." (PMID 35200716, 2022). "In our previous studies, we found that the ratio of CD4+/CD8+ T cells is increased during heart failure in rats and β1-AA has a profound impact on macrophages, which can directly activate resting macrophages and induce macrophages to secrete large amounts of cytokines." (PMID 35983976, 2022). "Heart failure patient biopsies revealed enhanced numbers of CD4+ Th1 and CD8+ T cells." (PMID 35200716, 2022).
heart failure (continued). "It is possible that the higher numbers of CD4+ T cells in the female hearts may be related to a reported role for these cells in heart failure, especially diastolic dysfunction." (PMID 32851570, 2021). "Thus, we propose that CD8+T cells suppress early phase protective heart hypertrophy while CD4+T cells suppress late phase destructive hypertrophy which leads heart failure." (PMID 34745139, 2021). "We have now addressed the question whether CD4+-T helper that possess specificity for an antigen expressed in cardiomyocytes are directly involved in the progression from hypertrophy to heart failure due to pressure overload." (PMID 29167489, 2017). "We investigated whether CD4+-T cells with specificity for an antigen in cardiomyocytes promote the progression from hypertrophy to heart failure in mice with increased pressure load due to transverse aortic constriction (TAC)." (PMID 29167489, 2017). "Collectively, our data indicate a critical role for TSLP in facilitating cardiac repair and conferring protection against MI, primarily through regulating CD4+ T cell responses, which may provide a potential novel therapeutic approach for managing heart failure after MI." (PMID 39703503, 2024). "CD4+ T cells also exhibit a characteristic biphasic activation during acute MI (reaching maximal activity in myocardial tissue 3 days after infarction) and heart failure (with a large spike in T-cell transmigration 20 times normal levels during congestive heart failure)." (PMID 38003879, 2023). "Regarding the MACCE rate at 30 days after discharge, patients with a low CD4+ nadir had more frequent acute coronary syndrome recurrence, more frequent hospitalizations for heart failure, and more deaths from cardiovascular causes, with no relevant differences." (PMID 37627941, 2023). "Therefore, CD4 + T cells are critical for the development of cardiac dysfunction that may result in heart failure." (PMID 35723764, 2022). "Moreover, T cell-deficient and T cell-depleted mice have been reported to be protected from heart failure induced by transverse aortic constriction (TAC) and we have shown recently that CD4+-helper T cells with specificity for an antigen in cardiomyocytes accelerate TAC-induced heart failure." (PMID 30498501, 2018). "Moreover, the enhanced CD4+ T cell activation observed in patients with heart failure in proportion to severity suggests that T cell-driven inflammation is one important pathophysiology of heart failure." (PMID 27135610, 2016). "CD4+CD28− T cells, which represent another subset with cytotoxic properties, predicted mortality in patients with AF and heart failure." (PMID 36611934, 2022). "We determined CD4+ T, CD8+ T and CD20+ B cells, monocytes and neutrophils per ml in pleural effusions of 22 LAC and 10 heart failure (HF) patients by flow cytometry." (PMID 30816121, 2019). "With heart failure in Chagas disease, myocardial levels of CD8+ and CD4+ T cells are increased, with a predominance of CD8+ T cells." (PMID 27795961, 2016). "CD4+ memory T cells, CD4+ T cells, CD4+ central memory T cells, CD8+ central memory T cells, and CD8+ T cells may contribute to AMI induced heart failure." (PMID 37334672, 2023). "Based on the relationship between T cells and acute heart failure, recent studies have continuously confirmed that the inflammatory response mediated by specific subpopulations of CD4+ and CD8+ T cells significantly affects the progression and prognosis of heart failure." (PMID 36186992, 2022). "The absence of CD4+T cells has been reported to alleviate heart failure in the chronic phase of TAC." (PMID 34745139, 2021). "In comparison to CD4+-T cells, CD8+-T cells with specificity for a model antigen in cardiomyocytes have little impact on the progression of pressure overload-induced heart failure." (PMID 30498501, 2018).
heart failure (continued). "Our data suggest that CD4+ and CD8+ T cells under myocardial overload in ADHF patients may be influenced by immune regulation to proliferate and activate participating in myocardial fibrosis and heart failure progression." (PMID 36186992, 2022). "Thus, CD8+-T cells with specificity for an antigen in cardiomyocytes, in contrast to CD4+-T cells, apparently do not have a major impact on progression and mortality of pressure overload-induced heart failure." (PMID 30498501, 2018). "Specifically CD4+-T cells appeared to be important since mice deficient for MHC class II molecules, which lack CD4+-T cells were protected from progression into heart failure after TAC similarly to RAG2-deficient mice lacking all T cells and in contrast to CD8-deficient mice lacking CD8+-T cells." (PMID 30498501, 2018). "WBC, suPAR, infiltrative CD68+, CD4+, CD54+, and HLA-DR+ cells did not correlate with any of the heart failure severity parameters." (PMID 34685378, 2021). "Changes of the percentage for CD3, CD4, CD8 and CD16 positive T cells were not significant due to low inflammatory reactivity in the pleural space of patients with cardiac failure." (PMID 27275329, 2016).
Hodgkins lymphoma (60 papers, 2004 to 2025). A heterogeneous group of malignant lymphoid neoplasms of B-cell origin characterized histologically by the presence of Hodgkin and Reed-Sternberg (HRS) cells in the vast majority of cases. "A previous study, performed in patients on cART or not in the Swiss HIV cohort, is in accordance with our findings, by showing a higher risk of Hodgkin lymphoma in patients having a very low CD4/CD8 ratio < 0.25, 1 to 2 years before diagnosis of malignancy." (PMID 27548257, 2016). "Based on our histological findings, we concluded that it was a rare form of CD4 positive Hodgkin lymphoma of the nodular sclerosis variant, with fast progression and resistance to conventional chemotherapy." (PMID 27429620, 2016). "Low CD4+ counts and intravenous drug use are risk factors for survival following a diagnosis of ADCs and Hodgkin lymphoma in the NADC group." (PMID 24760049, 2014). "An elevated CD4/CD8 T-cell ratio on flow cytometry (FCM) analysis has been reported in the literature to be associated with Hodgkin lymphoma (HL)." (PMID 16153296, 2005). "Finally, HBV positivity, lower haemoglobin level at NADC diagnosis and lower CD4 cell count were associated with mortality after Hodgkin’s lymphoma." (PMID 24106926, 2013). "However, the CD4 count was associated with mortality following a diagnosis of Hodgkin’s lymphoma and any NADC overall." (PMID 24106926, 2013). "However, Hodgkin's lymphoma incidence has an inverse relationship with CD4 count, in which moderate decreases in CD4 count greatly increase risk but risk decreases with severe immunosuppression." (PMID 19327166, 2009). "The inflammatory infiltrate in classical Hodgkin lymphoma is composed mainly of T cells (especially CD4 helper T cells, but also some CD8 cytotoxic T cells) and macrophages." (PMID 41256864, 2025). "We present a unique case of biopsy-confirmed BP in a 43-year-old man with advanced HIV infection (CD4 count: 4 cells/μL) and untreated classic Hodgkin lymphoma." (PMID 41328101, 2025). "The development of EBV-positive Hodgkin lymphoma has been previously reported in cases wherein CD4-positive lymphocytes in the peripheral blood recovered after HIV treatment." (PMID 38157001, 2024). "We used flow cytometry to demonstrate increased CD3+CD4+CD26− T‐cells in classic Hodgkin lymphoma (CHL), and designed a “Hodgkin score” to enhance separation of CHL from other reactive entities or T‐cell lymphomas." (PMID 39235202, 2024). "LAG-3 inhibits the antitumoral effect of anti-PD-1 and anti-LAG-3 therapy in Hodgkin lymphoma by inhibiting the CD4+ T-cell response." (PMID 37484526, 2023). "To validate the conclusion that TCR convergence was more prevalent in CD8+ T cells than in CD4+ T cells, we used another bulk TCRβ data collected from patients with classical Hodgkin lymphomas (cHLs)." (PMID 36350695, 2022). "The second finding in our study was an overexpression of LAG-3 on the CD4+ lymphocyte surfaces of the microenvironment of Hodgkin lymphoma, in patients exposed to anti-PD-1 immunotherapy." (PMID 34771650, 2021). "Another recent, elegant study in Hodgkin's lymphoma provided a detailed mapping of distances between tumor associated macrophages, labeled with CD68 and CD4+/CD8+ T cells." (PMID 30619287, 2018). "Elevated expression of PD-1 on CD4+ T cells in Hodgkin lymphoma negatively affects CD4+ T cells and is suspected to facilitate immune evasion of the tumor cells." (PMID 27815822, 2016). "Being a relatively cheap technique, aberrantly expressed T-cell antigens, particularly CD4, should be examined at baseline for every nodular sclerosis subtype classical Hodgkin lymphoma patient." (PMID 27429620, 2016). "Among 17 patients receiving HAART at diagnosis of Hodgkin lymphoma CD4 counts also declined, (mean change = −89 cells/μl, 95% CI −153 to −2; p = 0.04)." (PMID 24504076, 2014).